APLN (apelin)
Diseases named in the same sentence as APLN in open-access papers (continued):
Sharing a sentence is not in itself a finding about the gene and the disease.
heart failure (continued). "While the chemotactic and angiogenic activities of the native apelin and ELA peptides may have important implications in post-MI-related heart failure, they might, however, be detrimental in other conditions such as tumour growth." (PMID 37242650, 2023). "Previous clinical study has yielded that apelin was able to improve the predictive ability of the MAGGIC (Meta-Analysis Global Group In Chronic Heart Failure) and HFSS (Heart Failure Survival Score) scales adding new prognostic information to NT-proBNP in patients with severe HFrEF." (PMID 35050233, 2022). "Such a role in myocardial and pulmonary fibrosis could be particularly useful in treating heart failure and PAH where substantial fibrosis is known to occur in both organs and where apelin has already been identified as a potential therapeutic strategy." (PMID 31492821, 2019). "Moreover, apelin/APJ has been found to correlate with many cardiovascular diseases, such as atherosclerosis, coronary heart disease, heart failure, hypertension, pulmonary artery hypertension, myocardial ischemia–reperfusion injury and atrial fibrillation." (PMID 26142632, 2015). "In this work, the PPARα levels were significantly enhanced under treatment with the Apelin, suggesting that the PPAR plays a critical role in the rescue of the cardiac function in D-IRI rats and may be an important mechanism of anti-heart failure in D-IRI rats." (PMID 33342766, 2020). "Some reports point out that apelin does not reliably predict acute heart failure in patients presenting dyspnoea, and it is not a prognostic marker in those with confirmed heart failure or with chronic heart failure secondary to idiopathic dilated cardiomyopathy." (PMID 31653030, 2019). "Apelin level was found to be lower in uremic patients with dilated cardiomyopathy than in nonuremic counterparts; which leads to the speculation that uremia decreases apelin levels irrespective of the degree of heart failure." (PMID 24433492, 2014). "Apelin peptide (but not the target receptor) is significantly reduced in cardiovascular disease such as heart failure and pulmonary arterial hypertension (PAH), where the therapeutic hypothesis is that apelin receptor agonists are needed to replace the missing endogenous peptide." (PMID 31492821, 2019). "Recent studies indicate a role for the apelin–APJ signaling pathway in basic cardiac function and during the development of hypertension and there is growing evidence that apelin may be involved in the transition from compensated hypertrophy to clinically significant heart failure." (PMID 22197493, 2012). "The relationship between the apelin system and the ACE2 was proved previously, but their dynamics in the different stages of heart failure was not completely described and understood, and this study tried to bring more light into this problem." (PMID 34257745, 2021).
Insulin resistance (89 papers, 2008 to 2026). Increased resistance towards insulin, that is, diminished effectiveness of insulin in reducing blood glucose levels. "Our primary objective was to find an association between serum apelin levels and insulin resistance." (PMID 42211608, 2026). "It seems that high levels of fatty acids reduce cell sensitivity to insulin and eventually cause insulin resistance and hyperinsulinemia, which increases apelin secretion from adipose tissue." (PMID 37424869, 2023). "Several studies highlighted that increased serum levels of apelin are associated with increased adiposity, obesity, insulin resistance, MetS, and diabetes." (PMID 35406450, 2022). "Evidence showed that insulin resistance induced by a high-fat diet caused an increase in both apelin concentration and gene expression in adipose tissues." (PMID 31548844, 2019). "Treatment of diabetic rats withLC resulted in down regulation of Apelin axis in diabeticrats concomitant with improving insulin resistance andinflammatory markers and weight loss." (PMID 29845798, 2018). "Apelin plays a key role in the regulation of normal glucose and lipid metabolism and it is associated with insulin resistance." (PMID 25374607, 2014). "The synthesis of apelin in adipocytes is triggered by insulin and its plasma levels are reported to increase in association with insulin resistance and hyperinsulinemia." (PMID 24475149, 2014). "Consistent with its putative role as an adipokine, apelin has been linked to states of insulin resistance." (PMID 23437347, 2013). "Moreover, apelin-deficient mice showed decreased plasma adiponectin, increased insulin, impaired glucose and insulin tolerance, and insulin resistance." (PMID 37424869, 2023). "Reduced heart rate variability (HRV), insulin resistance (IR), dyslipidemia, and decreased vasodilatory adipokines, namely, apelin and relaxin, in normotensives may predispose to the onset of hypertension." (PMID 37799258, 2023). "Moreover, studies have reported that the apelin signalling pathway plays a vital role in neuroprotection, and insulin resistance is associated with neurodegeneration." (PMID 34868234, 2021). "Taken together, our results and those reported previously indicate that different associations between apelin and insulin resistance may depend on the extent of insulin resistance." (PMID 24475149, 2014). "In recent years, apelin has been linked to states of insulin resistance." (PMID 23437347, 2013). "However, the function of apelin in hepatic insulin resistance, a vital part of insulin resistance, and its underlying mechanisms still remains unclear." (PMID 23437347, 2013). "Body weight, lipid profile, glucose homeostasis, insulin resistance-related parameters, and circulating levels of apelin and irisin were evaluated." (PMID 42123645, 2026). "who, on the basis of their study, noted that apelin levels were clearly increased in patients with insulin resistance and hyperinsulinemia." (PMID 40491594, 2025). "Compared with adiponectin and apelin, described as beneficial adipokines, others, resistin and visfatin, are more deleterious in the context of insulin resistance, while leptin has a more controversial effect." (PMID 40943107, 2025). "From a pharmacological perspective, previous studies have demonstrated that both acute and chronic apelin treatment ameliorate insulin resistance and improve muscle functions." (PMID 39872377, 2024). "Apelin synthesis in adipocytes is elicited by insulin and its plasma level is increased in relation to insulin resistance and hyperinsulinemia." (PMID 37930396, 2024). "Apelin levels in the serum and adipose tissue are upregulated in obese and insulin-resistant mice, and apelin contributes to the regulation of food intake, cell proliferation, blood pressure, lipolysis, and glucose metabolism." (PMID 38672227, 2024).
Insulin resistance (continued). "Previous studies demonstrated that apelin directly enhances insulin sensitivity and suggested that the circulating apelin elevations observed in insulin resistance states are compensatory." (PMID 37930396, 2024). "Apelin was shown to suppress insulin resistance by increasing AMP-activated protein kinase (AMPK)-mediated glucose utilization and stimulating glucose transporter (Glut) 4, involved in the PI3K and Akt signaling pathways." (PMID 38672227, 2024). "In obese mice, treatment with apelin increases total body energy expenditure and reduces insulin resistance by increasing glucose uptake in skeletal muscle." (PMID 38887915, 2024). "Our study showed that the target genes of circ-Med14 were part of the MAPK and apelin signaling pathways, in addition to the progression of insulin resistance, hypertrophic cardiomyopathy, and chronic myeloid leukemia (CML)." (PMID 38967046, 2024). "Long-term HFD consumption by inducing insulin resistance and hyperinsulinemia increase apelin secretion from adipose tissue." (PMID 37424869, 2023). "In obese and insulin-resistant mice, chronic apelin treatment increases fatty acid oxidation in muscles by activating the AMPK pathway." (PMID 37424869, 2023). "Apelin is an adipokine having a compensatory role in reducing insulin resistance (IR) in morbidly obese individuals." (PMID 37706122, 2023). "Assuming that apelin exerts different regulatory roles according to insulin resistance levels can explain this contradiction." (PMID 36779088, 2023). "By inhibiting NLRP3 inflammasome, apelin ameliorates insulin resistance and promotes survival after severe burn in rats." (PMID 36779088, 2023). "Although apelin increases insulin resistance and appears to inhibit pancreatic insulin secretion, insulin sensitivity in animal models improved following apelin therapy." (PMID 36779088, 2023). "These same four miRNAs have different targets within the Apelin signaling in pancreatic cells in endothelial and vascular muscle cells leading to a predicted increase in insulin resistance and decrease in vasodilatation, respectively." (PMID 36747073, 2023). "Apelin has been shown to influence glucose and lipid metabolism as well as insulin resistance in animal models of type 2 diabetes." (PMID 37636297, 2023). "Higher plasma apelin levels in T2DM and T1DM prove this compensatory mechanism, which decreases insulin resistance and leads to a decrease in apelin levels." (PMID 38203346, 2023). "A significant decrease in skeletal muscle's apelin/APJ expression was noticed in animal models with severe insulin resistance." (PMID 36779088, 2023). "Treatment of mice with insulin resistance by apelin not only improves insulin sensitivity, but also increases fatty acid oxidation, oxidative phosphorylation, and mitochondrial biogenesis." (PMID 36093083, 2022). "Central administration of apelin in high doses in fasted mice provokes hyperinsulinemia, glucose intolerance and insulin resistance." (PMID 35406450, 2022). "Among them, 47 DMPs were significantly correlated with the expression of 36 corresponding genes, which were enriched in ‘insulin resistance’, ‘insulin signaling pathway’, and the ‘apelin signaling pathway’." (PMID 35685467, 2022). "Apelin, which is elevated in the serum of obese or diabetic individuals, has been reported to protect from hypertension, glucose intolerance and insulin resistance." (PMID 36289764, 2022). "Increased plasma apelin in type 2 and type 1 diabetic patients confirms the existence of this compensatory mechanism, which first reduces insulin resistance and then leads to a decrease in apelin levels." (PMID 36093083, 2022). "Apelin expression appears reduced in muscles of the elderly too and in mice with insulin resistance, and insulin resistance arises in cancer patients and in multiple cachectic models, including C26." (PMID 35406586, 2022).
Insulin resistance (continued). "In recent years, apelin has extensively received attention concerning its role in the progression of insulin resistance." (PMID 34660801, 2021). "It is believed that apelin can be used to reduce insulin resistance with the aim of improving altered glucose metabolism." (PMID 33743591, 2021). "It has been suggested that apelin secretion can be modulated by proinflammatory adipocytokines, the levels of which are higher in insulin resistance." (PMID 34212049, 2021). "It was found that apelin knockout mice exhibited an enhanced insulin resistance during high-fat diet feeding, which further confirmed the role of apelin in the regulation of glucose homeostasis." (PMID 33679444, 2021). "KEGG pathway analysis indicated that they were enriched in 2 pathways, including the apelin signalling pathway and insulin resistance." (PMID 34868234, 2021). "Clinical studies have demonstrated a relationship between apelin concentration and obesity and insulin resistance." (PMID 32375231, 2020). "Apln (Apelin) as a myokine has been used to improve metabolic effects by reducing obesity-related insulin resistance." (PMID 31998808, 2020). "Apelin is secreted from the white adipose tissue and plays an important role in energy metabolism and insulin resistance." (PMID 32300333, 2020). "It has been demonstrated that apelin-knockout mice develop insulin resistance but the adverse effects can be reversed by exogenous apelin treatment." (PMID 32375231, 2020). "Exposure to high fatty acid levels leads to insulin resistance and hyperinsulinemia, which subsequently rises apelin release from the adipose tissue." (PMID 31231491, 2019). "Apelin, as an adipokine, plays an important role in the pathogenesis of insulin resistance and type 2 diabetes." (PMID 31548844, 2019). "The role of apelin in insulin resistance has also been studied in mice with generalized apelin deficiency; these mice were insulin resistant and the resistance was reversed after exogenous apelin administration." (PMID 31492821, 2019). "In accordance with our results, previousworks showed that plasma Apelin level is elevated in patientsor animals with type II diabetes and insulin resistance." (PMID 29845798, 2018). "We observed that apelin overexpression in WJ-MSCs reduced insulin resistance, promoted ß cell replication and function recovery, and improved microcircumstance of pancreatic islets." (PMID 30526660, 2018). "The role of apelin in glucose homeostasis was confirmed by the phenotype of apelin null (apelin−/−) mice exhibiting hyperinsulinemia and insulin resistance." (PMID 25914650, 2015). "Recent data has focused on the roles of adipose tissue-derived mediators, such as adiponectin, leptin, resistin, tumor necrosis factor-alpha (TNF-α), visfatin, apelin, and chemerin in the pathogenesis of insulin resistance and inflammation." (PMID 23691290, 2013). "Apelin appears as a beneficial adipokine with anti-insulin resistance properties, and thus as a promising therapeutic target in metabolic disorders." (PMID 23437347, 2013). "Although it is difficult to reconcile these divergent findings, the data raise the possibility of alternative regulatory pathways for apelin production in the setting of insulin resistance." (PMID 23437347, 2013). "Findings from several studies suggest that apelin treatment during insulin resistance triggers a number of coordinated beneficial effects, including reduction of hyperinsulinemia and adiposity, and stimulation of glucose uptake and fuel consumption." (PMID 23227256, 2012). "Apelin is increased in relation to the worsening of insulin-resistance/insulin-secretion, as in the diabetic status, and this increase has been suggested as a possible compensatory mechanism." (PMID 23227256, 2012). "Apelin; endogenous ligand for the orphan receptor APJ, was recently suggested to be associated with fibrosis progression and cirrhosis in addition to insulin resistance (IR) and inflammation." (PMID 22007137, 2011).
Insulin resistance (continued). "However, despite the beneficial role of apelin in metabolic homeostasis, apelin concentration seems to be correlated with insulin resistance, probably explained by a compensatory effect." (PMID 40943107, 2025). "Recently, it has been more often suggested that apelin may increase insulin sensitivity and improve insulin resistance." (PMID 40491594, 2025). "Additionally, reduced BRS was correlated with waist circumference, insulin resistance, hyperinsulinemia, dyslipidemia, and reduced levels of apelin and relaxin." (PMID 37799258, 2023). "Because apelin appears to correct insulin sensitivity in conditions of severe insulin insensitivity, it may assist in the attenuation of burn-induced insulin resistance." (PMID 36779088, 2023). "In addition, analyses using liver and serum samples from non-NAFLD, NAFLD-NASH, and NASH-Cirrhosis patients revealed that TM4SF5 tended to increase as NAFLD developed along with serum apelin level enhancement, insulin resistance, and cholesterol enrichment." (PMID 37670786, 2023). "It was found that miR-140-5p may play a role in MAPK, Rap1, cAMP, PI3K-Akt, and Apelin signaling pathways, which are related to a variety of functions including insulin resistance and macrophage function." (PMID 38173723, 2023). "It has been found that the apelin levels are increased in insulin resistance." (PMID 38203346, 2023). "Therefore, optimal levels of apelin in blood circulation can probably be effective in delaying or reducing insulin resistance." (PMID 37424869, 2023). "In normal and insulin-resistant mice, apelin was noted to promote peripheral glucose uptake." (PMID 35355561, 2022). "Apelin protects from obesity, hypertension, glucose intolerance and insulin resistance." (PMID 36289764, 2022). "Because apelin stimulates glucose transport and acts additively to insulin, it is considered an important metabolic hormone that is also involved in the pathogenesis of insulin resistance and diabetes." (PMID 36611944, 2022). "Animal studies have revealed that apelin can improve glucose metabolism; therefore, it has been suggested that apelin could be a promising therapeutic target in the treatment of insulin resistance." (PMID 34212049, 2021). "Furthermore, we found that the secreted factors, myeloperoxidase was upregulated whereas apelin and myostatin were downregulated upon SARS-CoV-2 infection, which was potentially linked to the onset of insulin resistance." (PMID 34916489, 2021). "However, it is necessary to investigate the physiological function of the endogenous apelin changes induced by RK to determine the direct relationship of apelin with whole body insulin resistance." (PMID 34887778, 2021). "The hyperinsulinemic-euglycemic clamp experiment showed that intracerebroventricular (ICV) injection of high-dose apelin could reduce systemic sensitivity to insulin and produce insulin resistance." (PMID 33679444, 2021). "Very few data reported probiotics action on APLN levels, in 44 women affected by polycystic ovary syndrome, of which insulin resistance is the most important pathophysiologic characteristic, 12-week synbiotic supplementation decreases Apelin-36 serum concentration." (PMID 33171610, 2020). "In fact, it can be stated that the increase in the plasma level of apelin is a compensatory mechanism activated during insulin resistance because it has been found to increase the glucose uptake in the skeletal muscle and AT and repress lipolysis in healthy and insulin‐resistant rats." (PMID 33278072, 2020). "Recent studies have found high concentrations of apelin in obese individuals and in type 2 diabetes patients, while showing correlations of apelin with homeostatic model assessment-insulin resistance, body mass index, total cholesterol, low-density lipoprotein cholesterol, and insulin." (PMID 30696454, 2019).